ALB (albumin)
Diseases named in the same sentence as ALB in open-access papers (continued):
Sharing a sentence is not in itself a finding about the gene and the disease.
diabetes (continued). "In patients with AVC, the prevalence of hypertension, diabetes mellitus, ischemic heart disease, and left ventricular hypertrophy was significantly higher while the eGFR and serum albumin level were significantly lower than those in patients without AVC." (PMID 32471374, 2020). "One patient from the diabetes group had a transient increase in albumin-corrected calcium to 2.91 mmol/L on Day 1 after taking the drug; in all the other patients, the calcium levels did not exceed the reference range at any point of the study." (PMID 33352890, 2020). "We found that, in female PD patients, patients younger than 65 years old, patients with BMI ≥ 18.5 kg/m2 or albumin ≥35 g/L, and patients with a history of diabetes or cardiovascular diseases, the ratio has statistical significance." (PMID 32199459, 2020). "Patients with diabetes and/or elevated fasting blood glucose increase their exercise-induced urinary albumin excretion over time." (PMID 32539802, 2020). "urine albumin creatinine ratio (UAC) was calculated for 20 type 1 diabetes mellitus children in the endocrinology clinic after submitting early morning urine over a 4-month period." (PMID 32874425, 2020). "The SUA, homocysteine, and urinary albumin levels of individuals with diabetes in the PDR group were obviously higher than those of individuals with diabetes in the NPDR group (P < 0.05)." (PMID 33256661, 2020). "Among the common comorbidities, diabetes was observed to correspond to decreasing albumin levels over time, with a trend of − 0.001 (− 0.001 to 0.000)." (PMID 32295526, 2020). "Another possibility is residual confounding by poor nutritional status, since patients with low ionized calcium tended to have older age, lower BMI, lower albumin levels, and diabetes." (PMID 32157180, 2020). "The Diabetes Atherosclerosis Intervention Study (DAIS) showed that worsening of albumin excretion was reduced after the fenofibrate treatment." (PMID 32446306, 2020). "The association of waist circumference with metabolic syndrome was tested with adjustment for diabetes, HbA1c, body mass index, tobacco use, age, sex, statin treatment and serum albumin." (PMID 32792012, 2020). "A higher mortality rate in catheter users compared to fistula users abolished after correcting for age, gender, malnutrition, diabetes, hemoglobin, albumin and comorbidity in both patient groups." (PMID 32552698, 2020). "The positive rate of EUS-FNAB for the diagnosis of neoplasm and its associations with age, sex, target puncture mass size, liver function, tumor markers, albumin, hypertension, and diabetes were examined." (PMID 33162814, 2020). "Patients with FO > 15% before initiating SDHD was older, had a higher prevalence of diabetes and central intravenous catheter as the vascular access, and lower levels of serum albumin than the ones with FO ≤15%." (PMID 32349694, 2020). "The confounding factors were age, sex, the Japanese version of the Montreal Cognitive Assessment (MoCA-J), hypertension, diabetes mellitus, stroke, joint diseases, living alone, body mass index, and serum albumin." (PMID 32873231, 2020). "Data regarding signs of nephropathy were limited, with only 59 (17.9%) mothers with diabetes having a urine albumin/creatinine ratio available for the year prior to conception; of these, 14 had a result >3 mg/mmol." (PMID 31863141, 2020). "The risk of CVD death statistically significantly increased with the rise in LDL-C/HDL-C ratio in female PD patients, patients younger than 65 years old, patients with BMI ≥ 18.5 kg/m2 or albumin ≥35 g/L, and patients with a history of diabetes or CVD." (PMID 32199459, 2020). "These include clinical data e.g.: Serum Creatinine, Calcium, Phosphate, Bicarbonate, Albumin, eGFR, Albumin Creatinine Ratio, blood pressure, and for participants with diabetes: glucose and HbA1c." (PMID 32642867, 2020).
diabetes (continued). "Among the factors with high consistency of association, we found age, C-reactive protein, D-dimer, albumin, body temperature, SOFA score and diabetes." (PMID 32491116, 2020). "The laboratory findings showed blood glucose levels were higher and that AST or CRP elevation, anemia, and a low albumin level were more frequent in the diabetes group." (PMID 32933191, 2020). "The NFS score includes age, diabetes/hyperglycemia, BMI (body mass index), platelet count, albumin, and AST/ALT ratio, which were all independent indicators of liver fibrosis." (PMID 32025991, 2020). "Several factors involved in renal diabetic damage, such as Angiotensin II, glycated albumin and VEGF, induce nephrin downregulation in cultured podocytes." (PMID 31973092, 2020). "The multivariable analysis found all involved factors, except albumin and diabetes, to be significantly and independently predictive of the OS." (PMID 32140448, 2020). "Having demonstrated that both RIPK3 gene knockout and dabrafenib improved the fibrotic response induced by diabetes, we assessed the albuminuria with albumin-to-creatinine ratio (ACR)." (PMID 32591618, 2020). "Diabetes is a global epidemic, and the high cost of annually and quantitatively measuring urine albumin excretion using the turbidimetric immunoassay is challenging." (PMID 31961894, 2020). "The urine albumin test or albumin/creatinine ratio (ACR) is an indicator used to screen for damage to the kidney structures due to conditions such as diabetes and high blood pressure." (PMID 32026607, 2020). "RAAS inhibitors are also commonly prescribed to hypertensive patients with diabetes or chronic kidney disease (CKD) to reduce urinary albumin excretion and prevent or delay the onset of diabetic nephropathy and end-stage renal disease (ESRD)." (PMID 32241961, 2020). "Treatment with MMP-2/9 inhibitor I for 21 days, started six weeks after diabetes induction, restored endothelial glycocalyx depth and coverage and attenuated diabetes-induced albuminuria and reduced glomerular albumin permeability." (PMID 32037077, 2020). "These abnormalities mostly persisted during follow-up although some late improvements were observed particularly for total hemoglobin levels in participants with diabetes, and serum albumin in the overall sample." (PMID 32188410, 2020). "All patients demonstrated a significant loss of LTM over time, regardless of stratifying the covariates age, sex, LTI, baseline serum CRP, serum albumin, dialysis vintage, diabetes, or comorbidity index." (PMID 32824951, 2020). "We have previously determined that low plasma concentrations of certain ceramide species predict the development of nephropathy in diabetes patients with normal albumin excretion rates at baseline." (PMID 32045989, 2020). "The evaluation identified 12 of the features as most important, including tumor size and number, surgical extent, lymph node metastasis, hepatitis B surface antigen (HBsAg), AFP, CA19-9, CEA, albumin, platelet count, diabetes mellitus, and cholelithiasis." (PMID 32140448, 2020). "The models were developed separately for NAFLD-cirrhosis and ALD-cirrhosis and included seven predictors: age, gender, diabetes, BMI, platelet count, serum albumin and aspartate aminotransferase to ALT ratio." (PMID 32486355, 2020). "The main finding of this study is that patients with diabetes and/or elevated fasting blood glucose increase their exercise-induced urinary albumin excretion over time." (PMID 32539802, 2020). "Our study revealed a particularly high rate of PAOD in patients with higher plasma LRG1 levels, even after adjustment for diabetes, albumin and hsCRP levels." (PMID 32249825, 2020). "Increased urinary albumin excretion (UAE) in diabetes is a sensitive marker of microvascular injury and a reliable predictor of cardiovascular outcomes." (PMID 32252655, 2020).
diabetes (continued). "The multivariable analysis demonstrated that older age, smoking status, the presence of diabetes mellitus and coronary artery disease, and low albumin levels were independently correlated with adverse CV events." (PMID 32286459, 2020). "Several studies have described age, diabetes, cirrhosis, low platelet count and low albumin levels as significant prognostic factors for NAFLD/NASH." (PMID 33148171, 2020). "Numbers of patients with chronic liver disease, CVA, diabetes mellitus, as well as serum levels of albumin, K, Ca, and parathyroid hormone, transferrin saturation, hemoglobin and platelets were similar between the groups." (PMID 31999778, 2020). "For all patients with diabetes, current UK guidelines recommend routine testing of creatinine, urea, and electrolytes, urine albumin to creatinine ratio, and HbA1c." (PMID 33278890, 2020). "As diabetes epidemy increases, particularly in low-income countries, efficient and low-cost methods to measure urinary albumin are needed." (PMID 32138353, 2020). "Age, diabetes mellitus (DM), thrombocytopenia, hypoalbuminemia, liver cirrhosis, TNM stage, histology stage, vascular invasion, post-operative first year albumin and ALBI grade were significantly associated with RFS." (PMID 32350365, 2020). "Logistic regression was applied for cross-sectional analysis of the association between serum calcium level or albumin-corrected calcium (ACCA) and the prevalence of MetS, diabetes, or hypertension." (PMID 32081877, 2020). "The data showed that compared with the control group, the expression levels of CASP3, VCAM-1 and HGF were down-regulated in patients with syphilis and diabetes, while ALB, FN1, MMP9, IL8, CTGF, STAT3 and IGF1 were up-regulated." (PMID 32342229, 2020). "Univariate analysis showed that CKD3, CKD4, CKD5, B1 cells, B2 cells, NK cells, age, hypertension, systolic pressure, diabetes, hemoglobin, SCr, cystatin C, albumin, and triglyceride were prognostic factors for overall survival." (PMID 32266271, 2020). "We analyzed the long-term effect of these insulin fused to apolipoprotein A-I or insulin fused to albumin using AAVs in the db/db mouse model of diabetes, obesity, and liver steatosis." (PMID 33679386, 2020). "All miRNAs showed a higher importance compared to other components of the AURORA Risk Score such as albumin, history of CVD and history of diabetes." (PMID 32754270, 2020). "Multivariable-adjusted logistic regression models, including age, diabetes mellitus, albumin, and hemoglobin, were used to investigate the independent association between factor A, factor B, and time to dialysis." (PMID 32200348, 2020). "We considered possible confounding factors as follows: age, sex, body mass index, diabetes mellitus, malignant disease, B-type natriuretic peptide, creatinine, albumin, and platelet, which differed between the low GBS and high GBS groups." (PMID 33348860, 2020). "Two Met residues in serum albumin (Met-111 and Met-147) are highly oxidized to Met sulfoxide in patients with diabetes and the higher Met sulfoxide content in apoA-I from diabetic patients is consistent with lipid peroxidation products levels in plasma." (PMID 33381523, 2020). "FKBPL was positively correlated with age, known duration of diabetes, C-peptide level, urinary albumin to creatinine ratio (ACR), and waist to hip ratio." (PMID 33303872, 2020). "Concerning diabetes comorbidities, 14.1% of patients had a retinopathy treated with laser, 36% had a urinary albumin/creatinine ratio >3 mg/mmol, and mean eGFR calculated by MDRD was 76+/-20 ml/min." (PMID 32092076, 2020). "An MLP was constructed with six variables (age, diabetes, hypertension, hemoglobin, albumin, and calcium) collected retrospectively from an internal validation group (n = 129)." (PMID 32596403, 2020).
diabetes (continued). "The univariate Cox regression analysis showed that the age of starting hemodialysis, diabetes, serum albumin, vascular access and UA concentration and its variability interaction were risk factors for all-cause mortality." (PMID 32076464, 2020). "The interaction of factor A with factor B was independently associated with time to dialysis in regression models after adjustment for age, diabetes mellitus, albumin, and hemoglobin." (PMID 32200348, 2020). "Navigator-database reports and diabetes-care values (blood pressure, BMI, HbA1c, low-density lipoprotein, albumin-creatinine, smoking status) were collected." (PMID 33136062, 2020). "On day 28 after the onset of diabetes, urine albumin excretion, estimated as the albumin-to-creatinine ratio (ACR), was significantly higher in STZ-diabetic mice (CTL) than in healthy mice." (PMID 30872726, 2019). "Tofogliflozin also significantly reduced glycated albumin (P < 0.0001), which is a marker of monitoring and screening of type 2 diabetes mellitus, as well as a predictor of long‐term outcomes of the disease." (PMID 31033218, 2019). "Treatment with GSK‐J4 significantly ameliorated diabetic urinary total protein release, kidney weight index, and urinary albumin leakage, as well as attenuated diabetes‐induced apoptosis of glomerular cells (TUNEL assay)." (PMID 30948420, 2019). "After grouping based on ABI, the proportion of men and smoking, daily urine albumin excretion, HbA1c level, eGFR, and use of antiplatelets were higher and diabetes duration was longer in patients with ABI < 0.9." (PMID 31083218, 2019). "We assessed the long-term effect of multiple intravitreal anti-VEGF injections on measures of renal function in patients with diabetes including rate of change of estimated glomerular filtration rate (eGFR) and urine albumin-to-creatinine ratio (ACR)." (PMID 31878889, 2019). "The report also suggested that diabetes is the second major factor after that contributes to urinary albumin level." (PMID 31828155, 2019). "Urinary albumin excretion measurements revealed an increase in diabetic mice, a common finding in several other models of diabetes." (PMID 31798462, 2019). "At the end of study, STZ-induced diabetes groups of mice showed a markedly increase in 24-hour urinary albumin excretion and UACR ratio, compared to control groups." (PMID 31406124, 2019). "Pearson correlation analysis showed that plasma chemerin levels were positively related to duration of diabetes, serum creatinine, and 24-hour urine albumin excretion, even after multiple adjustments." (PMID 31379940, 2019). "If a patient with diabetes mellitus has an albumin excretion rate (AER) of 10mcg/min on a single sample then the probability of this exceeding a true threshold of 20mcg/min would be very low." (PMID 30811495, 2019). "In multivariable analysis, eGFR, diabetes mellitus, and serum albumin level were identified as independent predictors of CIN." (PMID 31057617, 2019). "Many factors can reduce albumin synthesis, including malnutrition, inflammation, diabetes, liver disease and sepsis; and greater catabolism, vascular permeability and renal or enteric loss can also lead to low serum albumin concentration." (PMID 31427625, 2019). "The variables used as covariates were as follows: age, sex, eGFR, presence of diabetes mellitus, mean arterial blood pressure for hypertension, serum albumin and proteinuria." (PMID 31040373, 2019). "Diabetes caused a significant elevation of AST, ALT, and ALP and a significant lowering of serum albumin." (PMID 32128099, 2019). "In the WSJPR treatment group, WSJPR efficiently attenuated diabetic renal injury via improvement of the serum TP and ALB, reduction of the excretion rate of U-TP, U-ALB, UUN and alleviation of mesangial matrix expansion and glomerular basement thickening." (PMID 31362740, 2019).
diabetes (continued). "The severe calcification group was older, had higher prevalence of type 2 diabetes mellitus, former cardiologic events, and lower albumin serum levels than the mild-moderate calcification group." (PMID 31138150, 2019). "Multivariate analysis showed that diabetes (HR 4.2 95% CI 1.2–14.2, p = 0.02), age and low albumin significantly predicted the development of HCC, differently from other metabolic risk factors, such as BMI." (PMID 31717576, 2019). "Here, the combinatorial impact of two stressful agents in diabetes on the metabolome of kidney cells was investigated, revealing effects of glucose and albumin on polyol metabolism in human proximal tubular cells." (PMID 31554337, 2019). "Variables that were significant in univariate analysis, such as albumin, history of intensive care unit stay, hypertension, and diabetes mellitus, were included as adjusting covariates in multivariate analysis." (PMID 30808972, 2019). "In diabetes, differences in beta and gamma globulins and low albumin levels have been reported and the ability of Lycopene to maintain these within normal ranges demonstrated its therapeutical advantages in alternative and complimentary medicine." (PMID 31831054, 2019). "Among all 417 patients, patients with and without VO had significant differences in gender, hypertension, diabetes mellitus, neoadjuvant chemotherapy, preoperative serum albumin, and synchronous metastasis." (PMID 31788654, 2019). "In the univariable analysis, increased total mortality was associated with increased age, E/Ea, and E/LA strain, the presence of diabetes, coronary artery disease, and chronic heart failure, and decreased albumin and LA strain." (PMID 31905735, 2019). "There were significant associations of the VFA categories with age, sex, BMI, ASA score, diabetes mellitus, sarcopenia, neoadjuvant chemotherapy, clinical stage, preoperative albumin, and surgical approach." (PMID 31929799, 2019). "They finally emphasized that abnormal MFR is strongly related to diabetes and the severity of albumin secretion in urine." (PMID 31237136, 2019). "After adjusting for age, sex, diabetes, cardiovascular disease, hypertension, eGFR, albumin level, and hemoglobin, the mortality rate was higher in the higher TBil group than in the lower TBil group (HR = 1.69, 95% CI: 1.11–2.56, p = .014)." (PMID 31240974, 2019). "In summary, serum bilirubin was associated with haemoglobin concentration, platelet count, serum albumin, triglycerides, duration of diabetes and smoking status in a Han Chinese population with T2DM." (PMID 31427625, 2019). "Glycated albumin has been already adopted by some Asian countries due to its usefulness in diabetes screening." (PMID 30591815, 2019). "In a 2011 study from Canada on an ESRD prediction model for CKD patients, the constructed model included age, sex, systolic pressure, diastolic pressure, albumin, phosphorous, calcium, hypertension, and diabetes." (PMID 31261555, 2019). "In patients with diabetes, a statistically positive relationship was found between albumin and GFR for T1DM (R = 0.264; p=0.04) and for T2DM (R = 0.283; p=0.01)." (PMID 31933638, 2019). "The model includes simply available covariates, such as age, gender, diabetes, BMI, platelets, albumin and AST to ALT ratio, exhibiting an area under the receiver operating characteristic curve (AUROC) of 0.75." (PMID 31717576, 2019). "For men, after adjusting for age, spouse, subjective economy status, diabetes, hypertension, hemoglobin, albumin, total cholesterol, and 25(OH) vitamin D (Model 1), WHODAS-12 was significantly associated with Kaigo-Yobo (β = 3.109, p < 0.001)." (PMID 31336809, 2019). "Covariates of adjusted model of hospitalization included SBP, ALT, UA, K, P, ferritin, diabetes, ALB, CRP." (PMID 30759782, 2019). "The 24 hr urine level of albumin increased in diabetes (P<0.001) and groups IV, V (P<0.01), VI (P<0.001), VII (P<0.01), VIII (P<0.01), and IX (P<0.001) versus the control group." (PMID 32133060, 2019).